BMI1 (BMI1 proto-oncogene, polycomb ring finger)
Diseases named in the same sentence as BMI1 in open-access papers (continued):
Sharing a sentence is not in itself a finding about the gene and the disease.
breast carcinoma (continued). "In contrast, overexpression of EZH2 and BMI1 were reported to have different influences on patient prognosis in breast cancer, and was found to have no prognostic value in urothelial carcinoma of the bladder." (PMID 25243792, 2014). "Expression of Bmi1 was found in most non-neoplastic tubular epithelial cells in breast tissue, and was also found in a large proportion of breast cancer (79.35%, 73/92) by immunohistochemistry." (PMID 24559156, 2014). "Our findings indicate p21/p16 and BMI1/c-MYC could serve as functional targets of dietary factor, GE, to inhibit early breast carcinogenesis and prevent breast cancer." (PMID 23342141, 2013). "Consistent with our previous reports that Bmi-1 could regulate Akt activity in breast cancer cells and the Akt/GSK-3β/Snail pathway in NPC cells, the overexpression of Bmi-1 facilitated the expression of phosphorylated Akt." (PMID 21276221, 2011). "In this study, the Bmi-1 protein seemed to localize in the nucleus of the breast cancer cells and in the cytoplasm of the non-cancer cells." (PMID 21276221, 2011). "Bmi-1 expression was significantly up-regulated in breast cancer tissues compared with the adjacent non-cancerous tissues, which was echoed by our previous reports." (PMID 21276221, 2011). "MiR-200c and miR-214 were previously reported to target BMI1 and EZH2, respectively, in studies that showed that miR-214 targets Ezh2 in skeletal muscle and embryonic stem cells and that miR-200c targets BMI1 in breast cancer stem cells." (PMID 21572997, 2011). "Furthermore, Bmi-1 plays a crucial role in invasion and metastasis by modulating the Akt/GSK-3β/Snail pathway and the expression of EMT markers in breast cancer." (PMID 21276221, 2011). "Bmi-1 was strongly up-regulated in breast cancer tissues compared with paired non-cancerous tissues, whereas E-cadherin was markedly down-regulated." (PMID 21276221, 2011). "BMI-1 is overexpressed in breast cancer cells growing as non-adherent mammospheres, and a BMI-1-based 11-gene signature is a powerful, therapy-independent predictor of recurrence, distant metastasis and death in 11 epithelial and non-epithelial cancers." (PMID 24212666, 2011). "We also compared the Bmi-1 mRNA expression in 34 paired tissues, including breast cancer and matched adjacent non-cancerous tissues." (PMID 21276221, 2011). "We demonstrate that Bmi-1 not only is increased in breast cancer tissues compared with adjacent non-cancerous tissues but also is associated with clinical features, such as tumor size, lymph node involvement, distant metastasis and clinical stage." (PMID 21276221, 2011). "Bmi-1 mRNA is significantly up-regulated in adjacent normal breast tissue in breast cancer patients compared to normal breast tissue from noncancerous patients." (PMID 21162745, 2010). "Although high Bmi-1 overexpression is connected to poor prognosis in nasopharyngeal carcinoma and to non-small-cell lung cancer, breast carcinoma, and hepatocellular carcinoma, in our data, Bmi-1-negative tumours showed a correlation with poor prognosis." (PMID 20145620, 2010). "Putative breast cancer stem cells might express surface markers such as aldehyde dehydrogenase 1 (ALDH1) and BMI-1 proteins." (PMID 20010944, 2010). "We included MYC in the protocol because BMI1 was originally identified as an oncogene that cooperates with MYC in lymphoma production in mice, MYC is commonly amplified in human breast cancer, and several groups have reported that MYC is required for HMEC transformation." (PMID 17573968, 2007).
breast carcinoma (continued). "In addition to augmenting antitumor immunity, LSD1 ablation can suppress the stem cell-like properties of HNSCC, HCC, glioma, small cell lung cancer, and breast cancers of luminal-B, HER2-positive, and TNBC subtypes through attenuating Wnt/β-catenin, Notch, BMI1, and SOX2-deriven stemness signaling." (PMID 35455671, 2022). "Furthermore, we sorted the basal breast cancer patients from low to high according to their mRNAsi values and found that patients with high mRNAsi are usually accompanied by high expression of tumor stem-related genes such as KDM5B, BMI1, MYC, and EZH2." (PMID 34646403, 2021). "Interestingly, Wnt5a-mediated BMI-1 upregulation in breast cancer cells was observed only at the protein level and not at the mRNA level, indicating that this process is not regulated via transcriptional activation." (PMID 31382410, 2019). "PTC-209 strongly inhibits growth of colon cancer cells and CSC phenotype, and BMI1 downregulation using siRNA approach or its inhibition by histone deacetylase inhibitors (HDACi) and PLK1 inhibitors is known to induce premature senescence in normal and breast cancer cells." (PMID 27105531, 2016). "Thus, by inhibiting BMI1, PTC-209 strongly induces premature cellular senescence in normal fibroblasts and breast cancer cells suggesting that PTC-209 also inhibits cancer cell growth via induction of premature senescence, which is a known tumor-suppressive mechanism." (PMID 27105531, 2016). "Because both protein and mRNA levels of Bmi1 were decreased in ERα-positive T47D cells relative to ERα-negative breast cancer cell lines, we determined whether ERα signaling played a role in Bmi1 expression." (PMID 26023734, 2015). "Indeed, isolated CD44+/CD24−/lowLin− CSCs express a five-fold increase in BMI1 compared to tumour cells also derived from the same human breast carcinoma-derived xenograft tumour, but lacking CSC marker expression." (PMID 26270676, 2015). "In the current study we have investigated the effects of Bmi1 overexpression and down-modulation on the expression of genes that regulate EMT and stemness, and further explored the molecular mechanisms downstream of Bmi1 that regulate EMT and stem cell properties in breast cancer cells." (PMID 25348805, 2014). "However, direct interaction exists only between cyclin D1 and ERα rather than Bmi1, and the expression of cyclin D1 in breast cancer probably reflects the regulatory effect of ERα." (PMID 24559156, 2014). "However, there has been no demonstration of any relationship of Bmi1 with other significant factors in breast cancer such as ERα, PR, HER2 and Ki-67." (PMID 24559156, 2014). "However, to our best knowledge, there is so far no study in the literature on the therapeutic potential of Bmi-1 in breast cancer cell lines." (PMID 21637439, 2009). "Although BMI1 expression does not seem to be restricted to ER-positive cells in normal mammary gland tissue, we found a strong correlation between BMI1 overexpression and positive ER status in the human breast cancer samples." (PMID 19099573, 2008). "However, in breast cancer, FUNDC1 likely functions as a tumor promoter through different mechanisms, in which depletion of FUNDC1 blocks TNBC cell proliferation by deregulating Ca2+ release from the ER and through NFATC1 activation, which are reversed by overexpression of BMI1." (PMID 36831455, 2023). "Besides Bmi-1, the PI3K/Akt cascade is also involved in regulation of the IR-induced EMT process and migration of breast cancer cells demonstrated by the results showing that either PI3K inhibitor or Akt inhibitor can abolish the inducibility of the effect of IR on breast cancer cells." (PMID 25734775, 2015). "In breast cancer stem cells (bCSCs), BMI1 has been located to stalled replication forks to recruit Rad51 and activate HRR pathways, whereas BMI1 cannot activate HRR pathways in non-bCSCs." (PMID 35875146, 2022).
breast carcinoma (continued). "It has been reported that PD-L1 expression sustains stemness factors OCT-4A and Nanog, via a PI3K/AKT-dependent pathway, and promotes expression of the stemness controlling factor BMI1, independent of PI3K/AKT in breast cancer cells." (PMID 35794161, 2022). "Although Bmi-1 overexpression alone did not result in oncogenic transformation of MCF-10A cells, overexpression of Bmi-1 together with H-Ras did induce an aggressive and metastatic phenotype, with the unusual occurrence of breast cancer brain metastasis." (PMID 21276221, 2011). "Moreover, we observed significant upregulation of several crucial stem cell factors such as Myc, Sox9 and BMI1 in response to elevated expression of KLF4 but not KLF4-3K, which suggests a critical role of KLF4 in the maintenance of self-renewal for breast cancer stem cell." (PMID 26420673, 2015).
glioma (109 papers, 2009 to 2026). A benign or malignant brain and spinal cord tumor that arises from glial cells (astrocytes, oligodendrocytes, ependymal cells). "Mechanically, this effect of miR-128 in GBM was associated with self-renewal inhibition of glioma stem cells (GSC) through the Bmi-1 pathway." (PMID 36834933, 2023). "miR-128 specifically inhibited glioma self-renewal, which was associated with decreased Bmi-1 expression." (PMID 36793341, 2022). "Mechanistically, this effect of miR-128 in GBM was linked to inhibition of self-renewal of glioma stem cells (GSCs) via the Bmi-1 pathway." (PMID 34434499, 2021). "Elevated levels of Bmi1 are associated with a poor prognosis in patients with head and neck cancer, nasopharyngeal carcinoma, and glioma." (PMID 33788424, 2021). "In keeping with these data, increased tumour latency and a shift towards glioma of a lower histological grade were observed in an experimental murine glial tumour arising in ink4a/arf deficient mice bred into a Bmi1−/− background." (PMID 31988455, 2020). "As expected, luciferase activity in glioma cells was reduced by co-transfection of the BMI1 construct and miR128-1, while mutation of BMI1's 3′-UTR miR128-1 binding sites abrogated reduction of luciferase activity by miR128-1." (PMID 27705931, 2016). "The Polycomb complex protein BMI1 is a stem cell regulatory gene implicated in the pathogenesis of many aggressive cancers, including glioma." (PMID 25726526, 2015). "IHC analysis of 127 cases of clinical human glioma specimens revealed that upregulation of Bmi-1 was associated with in an upregulation of MMP-9 and nuclear localization of NF-kappaB." (PMID 22967049, 2012). "Previous studies have indicated that Bmi-1 is overexpressed and associated with poorer overall survival in glioma." (PMID 22967049, 2012). "We also demonstrated that the ability of Bmi-1 to stimulate the invasive phenotype in glioma cells was mechanistically associated with activation of NF-kappaB and subsequent upregulation and activation of MMP-9." (PMID 22967049, 2012). "In addition, a previous study indicated that BMI1 was a potential oncogene associate with tumorigenesis and cancer progression in glioma." (PMID 32099526, 2020). "The role of USP22 and BMI1 in glioma associated stem cells has also been reported." (PMID 34660907, 2020). "The aim of the present study was to elucidate whether Bmi-1 expression was associated with the senescence of the U87 glioma cells that have been exposed to X-ray radiation." (PMID 25364434, 2014). "Also, its presence is required for malignant transformation of NSCs and astrocytes; high levels of Bmi-1 expression facilitate high-grade gliomas in vivo, while low expressing Bmi-1 cells initiate or are associated with less malignant glioma." (PMID 23998913, 2013). "Bmi-1, an onco-protein, has been implicated in the progression of various human cancers, including gliomas, whereas its role in glioma angiogenesis remains unclear." (PMID 23383216, 2013). "In the present study, the effects of melatonin on the transcriptional regulation of three genes associated with cell proliferation (Nestin, Bmi-1 and Sox2), and on C6 glioma cell survival and viability, were investigated in vitro to evaluate the use of melatonin in cancer therapy." (PMID 24137328, 2013). "The oncoprotein B-cell-specific Moloney murine leukemia virus integration site 1 protein (Bmi-1) has been linked to the development and progression of glioma; however, the biological role of Bmi-1 in the invasion of glioma remains unclear." (PMID 22967049, 2012). "In a mouse glioma model, Bmi1 was implicated in tumorigenesis in an Ink4a/Arf-independent manner." (PMID 19823589, 2009). "Downregulation of BMI1 has been shown to inhibit glioma cell proliferation, decrease telomerase expression, and increase sensitivity to chemotherapy." (PMID 41141394, 2026).
glioma (continued). "BMI1 expression levels are significantly higher in glioma tissue than in normal brain tissue; however, BMI1 alone cannot be used as a reliable indicator of patient survival." (PMID 41141394, 2026). "On the other hand, miR‐194, miR‐429, and miR‐340 demonstrate tumor suppressive properties in GBM by targeting Bmi‐1 to suppress glioma cell migration, invasion, and epithelial‐to‐mesenchymal transition." (PMID 39791545, 2025). "The BMI1 protein has been found to be also involved in the development and DR of canine and human gliomas, through the generation of stem cells from astrocytes." (PMID 40563676, 2025). "The incidence of Bmi‐1 positivity is augmented in grades II‐IV in human gliomas, and Bmi‐1‐positive cells frequently hold clinical importance in prognostic evaluations of overall survival in patients with glioma." (PMID 39791545, 2025). "MiR‐128's direct regulation of Bmi‐1 by miR‐128 in SVZ‐derived NSCs decreases glioma cell proliferation in vitro and in vivo and reduces GSC self‐renewal capacity." (PMID 39791545, 2025). "Independent studies have demonstrated that sonic hedgehog (Shh) signaling regulates Bmi‐1 expression in gliomas." (PMID 39791545, 2025). "Bmi‐1 tends to protect glioma cells against cytotoxic reagent‐induced cell death via its activation of the NF‐κB‐mediated anti‐apoptotic pathway." (PMID 39791545, 2025). "Gli1 and Gli2 control the expression of Bmi‐1 by their binding to the Bmi‐1 promoter and eventually upregulating multidrug‐resistant proteins that promote chemoresistance in glioma cells." (PMID 39791545, 2025). "Hsa-miR-194-5p is downregulated in gliomas and targets Bmi1 to decrease epithelial-to-mesenchymal transition." (PMID 38342922, 2024). "Drug resistance and stemness in GBM were also associated with Sp1 in another study and in glioma, HDAC/Sp1 regulation of BMI1 enhanced stemness; this exhibited some overlap with lung cancer cells and BMI1." (PMID 36982239, 2023). "High levels of miR-128 have been shown to inhibit glioma cell proliferation in vitro and tumor heterograft growth in vivo by directly regulating the Bmi-1 gene." (PMID 36834933, 2023). "miR-128 inhibits the proliferation, invasion, and self-renewal of GBM and glioma stem cells through the BMI1 and E2F3 pathways." (PMID 36834933, 2023). "A high expression of BMI1 is associated with poor outcomes in the patients with NPC, glioma, HNSCC, and NSCLC." (PMID 35455671, 2022). "ANGPTL4 overexpression can lead to the enrichment of glioma stem-like cells (GSCs), which is distinguished by the level of polycomb complex protein BMI-1 and SOX2." (PMID 36247876, 2022). "The experimental results showed that treatment with 8 μM WP1066 reduced the expression of stem cell‐related markers Oct4, Bmi1, and Sox2 in glioma cells after EMT." (PMID 33788424, 2021). "Ectopic expression of miR-128 remarkably suppresses glioma cell proliferation in vitro and glioma xenograft growth in vivo as well as self-renewal by targeting oncogene Bmi-1." (PMID 32993809, 2020). "Under hypoxic conditions, USP22 stabilizes BMI1 to induce CSC formation for cancer progression in glioma models." (PMID 34660907, 2020). "In this study, we revealed that BMI1 expression was markedly upregulated in glioma tissues and cells, which was consistent with previous research." (PMID 32099526, 2020). "In glioma, proteins such as Sox2, Bmi1, hairy and enhancer split (Hes) play crucial roles in neural development and promote self-renewal and proliferation in glioma." (PMID 31992303, 2020). "The expression levels of DANCR, miR-135a-5p and BMI1 were measured by qRT-PCR in glioma tissues and cells." (PMID 32099526, 2020). "DANCR knockdown inhibited cell proliferation, migration and invasion in glioma cells through regulating miR-135a-5p/BMI1 axis, providing viable therapeutic avenues for treatment of glioma." (PMID 32099526, 2020).